SNX11 (sorting nexin 11)
Description:
Phosphoinositide-binding protein involved in protein sorting and membrane trafficking in endosomes. Regulates the levels of TRPV3 by promoting its trafficking from the cell membrane to lysosome for degradation.
Tractability: Small molecule: a structure with a bound ligand is known. Antibody: UniProt places it where antibodies can reach, with high confidence; its Gene Ontology location is reachable by antibodies, with high confidence. PROTAC: ubiquitination databases record sites on it; its protein half-life has been measured.
Gene: Protein-coding gene on chromosome 17 (48,103,357 to 48,123,601, forward strand). Ensembl gene ENSG00000002919.
Subcellular location: Cell membrane; Endosome; Cytoplasm
Subcellular location (Human Protein Atlas): Endoplasmic reticulum; Vesicles
Gene Ontology:
Molecular function: phosphatidylinositol phosphate binding; protein binding; phosphatidylinositol binding
Biological process: vesicle organization; intracellular protein transport
Cellular component: cytoplasm; endosome; plasma membrane
Genetic constraint (gnomAD): Loss-of-function variants: 17 observed, 28.83 expected, observed/expected ratio (o/e) 0.59, 90% interval 0.4 to 0.88. The upper end of that interval is the gene's LOEUF score, 0.88, which puts it in group 3 of 6, group 1 being the genes least tolerant of losing a copy. Missense variants: 289 observed, 328.05 expected, observed/expected ratio (o/e) 0.88, 90% interval 0.8 to 0.97. Synonymous variants: 108 observed, 121.61 expected, observed/expected ratio (o/e) 0.89, 90% interval 0.76 to 1.04.
Homologues: Orthologues: macaque SNX11 (94% identical), chimpanzee SNX11 (94% identical), dog SNX11 (90% identical), pig SNX11 (90% identical), rat Snx11 (87% identical), mouse Snx11 (84% identical), rabbit SNX11 (82% identical), guinea pig SNX11 (79% identical), zebrafish snx11 (49% identical), tropical clawed frog snx11 (48% identical), Drosophila melanogaster Snx6 (17% identical), Drosophila melanogaster Snx1 (17% identical), and 2 more. Paralogues in human: SNX10 (34% identical), SNX1 (23% identical), SNX2 (23% identical), SNX18 (18% identical), SNX3 (17% identical), SNX30 (17% identical), SNX4 (17% identical), SNX8 (17% identical), SNX12 (17% identical), SNX7 (17% identical), SNX33 (17% identical), SNX6 (16% identical), and 3 more.
Diseases named in the same sentence as SNX11 in open-access papers:
SNX11 is named in the same sentence as 5 diseases in open-access papers, as found by Europe PMC text mining. Sharing a sentence is not in itself a finding about the gene and the disease. The quoted sentences say what the papers report.
endometrial cancer (3 papers, 2019 to 2021). Primary or metastatic malignant neoplasm involving the endometrium (mucous membrane that lines the endometrial cavity). "Three of the TWAS candidate susceptibility genes (EIF2AK4, SKAP1, and SNX11) have been recently identified as potential regulatory targets of endometrial cancer GWAS risk variation through enhancer-promoter chromatin looping studies." (PMID 34675350, 2021). "Subsequent causal inference test by MR-JTI revealed two candidate genes for endometrioid endometrial cancer susceptibility (SNX11 and EIF2AK4), both of which had been identified in the main MR-JTI analysis using all endometrial cancer cases." (PMID 34675350, 2021). "To prioritise the genes identified by JTI, we performed a Mendelian randomization (MR) causal inference analysis in the respective tissues using MR-JTI, providing five candidate endometrial cancer susceptibility genes: CYP19A1, SNX11, AC021755.3, EEFSEC, and EIF2AK4." (PMID 34675350, 2021).
endometrial tumors (2 papers, 2019 to 2020). "Three of these associations were observed in whole blood (SNX11, HOXB2 and SRP14) and one in endometrial tumors (BCL11A)." (PMID 31561579, 2019).
diabetes (1 paper, 2021). "PheWAS analysis of the eight candidate susceptibility genes revealed that four candidate genes (CYP19A1, EIF2AK4, EVI2A and SNX11) associated with 56 traits related to seven phenotypic categories: anthropometric, bone health, cardiovascular, diabetes, hematopoiesis, liver function, and sex hormones." (PMID 34675350, 2021).
viral infection (1 paper, 2025). "While our study establishes SNX11’s role in v-ATPase assembly and endosomal acidification, broader functions of SNXs in viral infection warrant consideration." (PMID 40732723, 2025).
infection (1 paper, 2025). The state of being infected such as from the introduction of a foreign agent such as serum, vaccine, antigenic substance or organism. "At 96 h post-infection with Dabie bandavirus, the positive rate of viral nucleoprotein NP in SNX11-deficient cells decreased by 95% compared to the normal group." (PMID 40732723, 2025). "SNX11 knockout consistently inhibited infection by all tested viruses." (PMID 40732723, 2025). "This suggests that SNX11 likely facilitates infection indirectly via host pathway modulation rather than through direct virion binding." (PMID 40732723, 2025).